INCA1 (inhibitor of CDK, cyclin A1 interacting protein 1)
Description:
Binds to CDK2-bound cyclins and inhibits the kinase activity of CDK2; binding to cyclins is critical for its function as CDK inhibitor. Inhibits cell growth and cell proliferation and may play a role in cell cycle control (By similarity). Required for ING5-mediated regulation of S-phase progression, enhancement of Fas-induced apoptosis and inhibition of cell growth (By similarity).
Synonyms: HSD45
Tractability: No criterion of Open Targets' tractability assessment is met for any kind of drug.
Gene: Protein-coding gene on chromosome 17 (4,988,130 to 4,999,117, reverse strand). Ensembl gene ENSG00000196388.
Subcellular location: Nucleus; Cytoplasm
Subcellular location (Human Protein Atlas): Nuclear bodies; Nucleoplasm
Gene Ontology:
Molecular function: cyclin binding; cyclin-dependent protein serine/threonine kinase inhibitor activity; identical protein binding; protein binding; protein-containing complex binding
Biological process: negative regulation of cyclin-dependent protein serine/threonine kinase activity; negative regulation of cell population proliferation
Cellular component: cytoplasm; nucleus
Genetic constraint (gnomAD): Loss-of-function variants: 29 observed, 28.32 expected, observed/expected ratio (o/e) 1.02, 90% interval 0.76 to 1.4. The upper end of that interval is the gene's LOEUF score, 1.4, which puts it in group 5 of 6, group 1 being the genes least tolerant of losing a copy. Missense variants: 309 observed, 305.93 expected, observed/expected ratio (o/e) 1.01, 90% interval 0.92 to 1.11. Synonymous variants: 111 observed, 110.57 expected, observed/expected ratio (o/e) 1, 90% interval 0.86 to 1.17.
Homologues: Orthologues: chimpanzee INCA1 (98% identical), macaque INCA1 (95% identical), pig INCA1 (73% identical), guinea pig INCA1 (71% identical), rabbit INCA1 (69% identical), rat Inca1 (65% identical), dog INCA1 (64% identical), mouse Inca1 (61% identical).
Diseases named in the same sentence as INCA1 in open-access papers:
INCA1 is named in the same sentence as 7 diseases in open-access papers, as found by Europe PMC text mining. Sharing a sentence is not in itself a finding about the gene and the disease. The quoted sentences say what the papers report.
leukemia (2 papers, 2014 to 2020). A malignant (clonal) hematologic disorder, involving hematopoietic stem cells and characterized by the presence of primitive or atypical myeloid or lymphoid cells in the bone marrow and the blood. "As a consequence, leukemia induction and leukemia maintenance were severely impaired in Inca1−/− bone marrow cells." (PMID 25525809, 2014). "In addition, ZNF16 inhibited apoptosis and stimulated cell cycle progression by inhibiting INCA1 in K562 leukemia cells." (PMID 32460791, 2020). "The re-initiation of leukemia was also significantly inhibited in absence of Inca1−/− in MLL—AF9- and c-myc/BCL2-positive leukemia mouse models." (PMID 25525809, 2014). "We show that absence of Inca1 mildly affects normal hematopoiesis under homeostatic conditions but controls hematopoiesis after induction of cytotoxic stress and plays a role in the maintenance of leukemia development in acute myeloid leukemia." (PMID 25525809, 2014).
Acute Lymphoid Leukemia (1 paper, 2014). "Decreased INCA1 levels in blasts from Acute Lymphoid Leukemia (ALL) and Acute Myeloid Leukemia (AML) patients underlined its relevance for growth control in vivo and for the hematopoietic system." (PMID 25525809, 2014).
tumor (2 papers, 2011 to 2014). "We also discovered that the tumor suppressor Ing5 interacts with and depends on Inca1, further underlining a putative role of Inca1 in cancerogenesis." (PMID 25525809, 2014). "Our data show that by interacting with INCA1, ING5 exerts tumor-suppressive function by inhibiting colony formation and cell proliferation, and increasing Fas-antibody-induced apoptosis." (PMID 21750715, 2011). "Among the nine interacting partners of INCA1, ING5 is a new member of the candidate tumor-suppressor ING family." (PMID 21750715, 2011).
cancer (1 paper, 2015). A tumor composed of atypical neoplastic, often pleomorphic cells that invade other tissues. "For instance, INCA1, whose methylation was about 12% lower at 6 month after RYGB than it had been at baseline, may have an anti-cancer effect due to its anti-proliferative properties." (PMID 25710379, 2015).
INCA1 also shares sentences with these, for which no sentence is quoted: acute myeloid leukemia (1 paper); infection (1); nasopharyngeal carcinoma (1).